SLC5A8 (solute carrier family 5 member 8)
Diseases named in the same sentence as SLC5A8 in open-access papers (continued):
Sharing a sentence is not in itself a finding about the gene and the disease.
papillary thyroid carcinoma (3 papers, 2009 to 2025). "Since the mechanisms regulating SLC5A8 expression have not been thoroughly studied, we hypothesized that the lower expression of SLC5A8 in papillary thyroid carcinoma results from overexpression of its regulatory microRNAs." (PMID 40869209, 2025). "Moreover, we found an association of SLC5A8 and TIMP3 DNA methylation with BRAFV600E in our colorectal tumor samples, as had been previously reported in papillary thyroid carcinomas." (PMID 20027224, 2009). "SLC5A8 was postulated as a potent tumor suppressor and its lowered levels were shown in numerous malignancies, including follicular thyroid carcinoma and papillary thyroid carcinoma, where its suppression seems to be BRAF-dependent and is related to tumor aggressiveness." (PMID 40869209, 2025). "Our data shows that in papillary thyroid cancer (PTC) the overexpression of microRNAs, including miR-181a-5p, miR-182-5p, and miR-494-3p, may contribute to a reduced expression of the tumor suppressor SLC5A8." (PMID 40869209, 2025).
colon adenoma (2 papers, 2011 to 2024). An adenoma that arises from the colon. "SLC5A8 is highly methylated in AA colon adenomas which points to its potential use as a marker for early detection." (PMID 21687703, 2011). "SLC5A8 methylation and its relation with the colon adenoma subtype and adenocarcinomas." (PMID 21687703, 2011). "SLC5A8 methylation and clinicopathological properties colon adenoma." (PMID 21687703, 2011). "Here, we analyzed 50 colon adenomas from AA patients for both microsatellite instability (MSI) and the methylation status of SLC5A8 gene." (PMID 21687703, 2011).
gastritis (2 papers, 2016 to 2020). Inflammation of the stomach. "More severe gastritis (P = 0.019), and presence of lymphoid follicles (P = 0.044) were significantly associated with decreased SLC5A8 expression levels." (PMID 27777899, 2016). "Expectedly, H. pylori was associated with more severe gastric tissue damage, and more severe damage (gastritis severity and presence of lymphoid follicles) was associated with decreased SLC5A8 expression levels." (PMID 27777899, 2016).
hepatocellular carcinoma (2 papers, 2023 to 2025). A malignant tumor that arises from hepatocytes. "Furthermore, SLC5A8 has been implicated in exerting tumour-suppressive effects in hepatocellular carcinoma by disrupting the Wnt/β-catenin signalling pathway." (PMID 40181975, 2025).
lung carcinoma (2 papers, 2014 to 2021). "SLC5A8 has been shown to be a tumor suppressor in lung tumor and silenced by promoter hypermethylation in the development of lung cancer." (PMID 34136553, 2021). "This analysis resulted in 4 novel miR-21 putative target genes; solute carrier family 5 (iodide transporter) member 8 (Slc5a8), lipopolysaccharide binding protein (Lbp), V-myc myelocytomatosis viral oncogene homolog 1, lung carcinoma derived (Mycl1), PDZ and LIM domain 3 (Pdlim3)." (PMID 24497923, 2014).
undifferentiated carcinoma (2 papers, 2013 to 2019). A usually aggressive malignant epithelial neoplasm composed of atypical cells which do not display evidence of glandular, squamous, or transitional cell differentiation. "Hyper-methylation of SLC5A8 promoters reported preferentially in undifferentiated carcinoma." (PMID 31754358, 2019).
clear cell renal cell carcinoma (1 paper, 2022). "We selected lactic acid metabolism and transporter related twenty-one genes for LASSO cox regression analysis in the E-MTAB-1980 cohort, and finally screened three genes (PNKD, SLC16A8, SLC5A8) to construct a clinical prognostic model for patients with clear cell renal cell carcinoma." (PMID 35456426, 2022).
Constipation (1 paper, 2015). Infrequent or difficult evacuation of feces. "Of the ten up-regulated genes, the largest decrease in the transcripts of constipation rats was observed for Serpina3n (0.19-fold), followed Lcn2, Slc5a8, C3, Rerg, and Arhgap8." (PMID 26151867, 2015).
dental caries (1 paper, 2023). The decay of a tooth, in which it becomes softened, discolored, and/or porous. "Abnormal SLC5A8 expression disrupted ion and pH homeostasis and inhibited enamel crystal growth, which led to enamel hypomineralization and might contribute to the development of dental caries." (PMID 36981009, 2023). "A total of 39 independent vQTLs with p < 1 × 10−6 were identified, some of which were located in or near genes with plausible biological roles in dental caries (IGFBP7, SLC5A8, and SHH involved in tooth development and enamel mineralization)." (PMID 36981009, 2023).
goiter (1 paper, 2019). Enlargement of the thyroid gland usually caused by lack of iodine in the diet, hyperthyroidism, or thyroid nodules. "Our data showed that the promoter methylation of SLC5A8, Ras association domain family member 1(RASSF1), and MGMT were significantly different between PTC tissue and goiter with P-value less than 0.05." (PMID 31754358, 2019). "However, our results indicated that DNMT1 methylation in PTC patients, in comparison with goiter patients (controls), was less than SLC5A8, RASSF1, and MGMT." (PMID 31754358, 2019). "In this research, we determined the promoter methylation status of four tumor suppressor genes (SLC5A8, RASSF1, MGMT, and DNMT1) and compared the results of 55 PTC cases with 40 goiter patients." (PMID 31754358, 2019).
liver cancer (1 paper, 2025). An epithelial or non-epithelial malignant neoplasm that arises from the liver. "Overexpression of SLC5A8 mediates apoptosis induction for the antitumor response in liver cancer." (PMID 40548257, 2025).
thyroid (1 paper, 2023). "Some data from tissue DNA suggest that aberrant methylation of the SLC5A8 gene may be an early change in thyroid tumorigenesis, regardless of the cell type." (PMID 38007446, 2023).
thyroid tumor (1 paper, 2023). A benign or malignant neoplasm affecting the thyroid gland. "We used 165 tissue samples, including FTC (n = 58), thyroid tumors of uncertain malignant potential (TT-UMP, n = 40), and FTA (n = 67), to explore the differences in SLC5A8 methylation and mRNA transcription in different pathological types." (PMID 38007446, 2023).
ulcerative colitis (1 paper, 2019). An inflammatory bowel disease involving the mucosal surface of the large intestine and rectum. "In addition, the bacterial strains associated with disease remission in patients with ulcerative colitis, which include Staphylococcaceae, Lactobacillaceae, and Coriobacteriaceae, are also enriched in Slc5a8-null mice." (PMID 31976310, 2019).
undifferentiated thyroid carcinoma (1 paper, 2019). "CpG island methylation of tumor-related promoters including RASSF1, MGMT, and SLC5A8 occurs preferentially in undifferentiated thyroid carcinoma." (PMID 31754358, 2019).
villous adenoma (1 paper, 2011). An epithelial neoplasm morphologically characterized by the presence of a villous architectural pattern. "SLC5A8 methylation profile was similar in all 5 categories of samples used (TA, TVA, VA, AdeCA, and polyps) except for villous adenomas for which we had only two samples." (PMID 21687703, 2011).
tumor (58 papers, 2005 to 2025). "Silencing of SLC5A8 is associated with DNA methylation; treating tumor cells with DNA demethylating agents increases SLC5A8 expression." (PMID 40725030, 2025). "SLC5A8 encodes a sodium-coupled monocarboxylate transporter protein and has been noted by various studies to function as a tumor suppressor." (PMID 39408960, 2024). "Previous studies from our laboratory have shown that the Na+-coupled high-affinity monocarboxylate transporter Slc5a8 functions as a tumor suppressor only when diet is deficient in fiber." (PMID 31976310, 2019). "Moreover, in a combined analysis of SLC5A8 expression with tumour mutational burden (TMB), higher expression levels were associated with improved prognostic outcomes." (PMID 40181975, 2025). "Whilst in parallel, SLC5A8 levels in tumours were reduced compared to normal tissue and cell lines, which is consistent with previous studies showing an association between SLC5A8 down-regulation and tumour progression." (PMID 19689820, 2009). "Thus, this leads to the hypothesis that SLC5A8-mediated tumor growth inhibition is associated with transposing antiproliferative molecules into the cells, thereby improving mitochondrial function." (PMID 39061990, 2024). "Among microRNAs with putative binding sites in the 3′UTR of SLC5A8, miR-29a-3p, miR-92b-3p, miR-181a-5p, miR-182-5p, and miR-494-3p showed the highest upregulation and/or expression level in tumor tissue, and were chosen for further analyses." (PMID 40869209, 2025). "SLC5A8 is a protein coded by the SLC5A8 gene, and has been proposed as a tumor suppressor and iodide transporter." (PMID 40869209, 2025). "SLC5A8 (solute carrier gene family 5a, member 8), also known as SMCT1 or sodium-coupled monocarboxylate transporter 1, is a Na(+)-coupled high-affinity transporter membrane transporter that is considered a tumor suppressor by most authors." (PMID 38931411, 2024). "As a tumor suppressor, SLC5A8 has been observed to induce apoptosis by transporting short-chain fatty acids into tumor cells." (PMID 39408960, 2024). "Accumulating evidence has confirmed that SLC5A8 exerts proliferative effects on tumor-dearing and anti-tumor cell proliferation." (PMID 38007446, 2023). "Accumulating evidence has shown that SLC5A8 acts as a tumor suppressor and plays an important role in promoting tumor apoptosis and antitumor cell proliferation." (PMID 38007446, 2023). "Among them, the ‘HPV‐related normal cluster’ specifically expressed SLC5A8, a tumour suppressor gene, which has been reported to inhibit cell proliferation and regulate cell apoptosis." (PMID 36967539, 2023). "Studies revealed that tumor cells can inhibit the expression of slc5a8 on the apical membrane of colonocytes by preventing butyrate from entering cells." (PMID 34203243, 2021). "Previous studies have identified pyruvate as an HDAC inhibitor and indicate that tumor cells would silence Na + −coupled pyruvate transport SLC5A8, as well as convert pyruvate into lactate, as complementary mechanisms to avoid pyruvate-induced cell death." (PMID 30866966, 2019). "This also provided a mechanistic explanation for the tumor-suppressive function of the Na+-coupled SCFA transporter SMCT1 (SLC5A8) in the colon." (PMID 28796169, 2017). "Four out of six neoplasias were found in the mice showing higher methylation at CGIs of all five genes Dkk1, Slc5a8, Hoxd1, Socs1 and Sfrp1 (B219, B220), of the four genes Dkk1, Hoxd1, Socs1 and Sfrp1 (B215), or of Dkk1 (B236)." (PMID 24204690, 2013). "The group of Ganapathy has proposed an interesting model to explain the tumour suppressor activity of SLC5A8 specifically centered on the role of pyruvate." (PMID 23762063, 2013). "In mice fed with WD, proximal colon mucosa, the predominant site of cancer formation in LS, exhibited a significant expression decrease in tumor suppressor genes, Dkk1, Hoxd1, Slc5a8, and Socs1, the latter two only in the Mlh1+/- mice." (PMID 24204690, 2013).
tumor (continued). "As such, SLC5A8 gene product that is involved in its transport through the colon mucosa have been labeled as a tumor suppressor gene." (PMID 21687703, 2011). "The optimal transcript combination that separated tumour from normal was SLC5A8 and MMP-7 resulting in a leave-one-out error estimate of 0.128." (PMID 19689820, 2009). "In contrast to GLUT1, SLC5A8 has been shown to be highly expressed in the colon and to act as a tumor suppressor gene." (PMID 15882471, 2005). "In 43/49 (88%) tissue pairs, the expression of SLC5A8 was lower in tumor than control tissue." (PMID 40869209, 2025). "Notably, DPEP3 (dipeptidase 3), THRSP (thyroid hormone responsive), and SLC5A8 (solute carrier family 5 member 8) were significantly upregulated in high-grade tumors, suggesting roles in tumor progression and metabolic reprogramming." (PMID 41155123, 2025). "Hypermethylation of RASSF1 and SLC5A8 promoter regions was found to be higher in both tumor tissue samples and ctDNA of patients with PTC compared to those with benign thyroid nodules, and hypermethylation of the promoter regions of SLC5A8 in ctDNA was significantly associated with stage of PTC." (PMID 39335101, 2024). "Thus, abnormal DNA methylation of SLC5A8 is considered the standard for determining the specificity of tumor molecules, which has a guiding role in the early diagnosis and prognosis of cancers." (PMID 38007446, 2023). "SMCT1(SLC5A8) was initially discovered as a tumor suppressor." (PMID 35276983, 2022). "Like MCT1, SLC5A8 may act as a tumour suppressor as it mediates the uptake of butyrate, propionate and pyruvate." (PMID 36558520, 2022). "SLC5A8 functions as a tumor suppressor not only in the colon but also in a wide variety of tissues." (PMID 31976310, 2019). "There is also evidence that SLC5A8 might elicit its tumor-suppressive effects via a transport-independent mechanism involving interaction with survivin." (PMID 31976310, 2019). "SLC5A8 is a candidate tumor suppressor, whose expression is silenced in colon cancer." (PMID 31976310, 2019). "In addition to its transporter function, the SLC5A8 protein has a demonstrated role in tumor suppression through the active import of endogenous inhibitors of histone acetylases (HDACs) [i.e., butyrate, which originates from gut microbes, and pyruvate]." (PMID 24653705, 2014). "Recently, SLC5A8 was shown to counteract tumor progression independent from its transport function." (PMID 24653705, 2014). "Consequently, our proposal that ZIP1 is a tumor suppressor gene in prostate cancer is similar to the reported involvement of SLC5A8 as a tumor suppressor gene in colon and other cancers." (PMID 16700911, 2006). "Besides the Na+ dependent ileal bile acid transporter (Slc10a2) and Slc34a2, the sodium transporter Slc5a8, a tumor suppressor gene, was also more highly expressed in the ileum compared to the jejunum, but similarly expressed in the colon." (PMID 15882471, 2005). "Accordingly, it has been hypothesized that SLC5A8 may act as a tumour suppressor." (PMID 23762063, 2013). "Our study findings also revealed a noteworthy 2.5-fold upregulation of SLC5A8 and a 2.4-fold upregulation of SLC5A5 in the TERT-negative tumor as compared to the TERT-positive tumor." (PMID 38642578, 2024). "Five molecules (DAPK1, TIMP3, GRIN2B, SLC5A8, and CDH1) are tumor suppressor genes consistently downregulated and/or hypermethylated in GC and in H. pylori infected children." (PMID 32117120, 2020). "According to our knowledge, only two reports focused mainly on the 12q23.2, 16q11–q21 and 16q23-qter chromosomal regions (harboring SLC5A8,CDH1 and CDH3 gene loci) in lung cell lines and small cohort of tumours have been hitherto published." (PMID 24091944, 2013).
tumor (continued). "SLC5A8 and GPR43 are known to serve as tumor suppressors; mice lacking SLC5A8 develop CRC, while the activation of GPR43 prevents colon inflammation and carcinogenesis." (PMID 34068653, 2021). "Not only have known tumor suppressor genes like Cdkn2a (p16), Itga4 (α 4-integrin), and Igfbp7 been identified as targets of aberrant methylation in cancer by RLGS, but also novel tumor suppressor genes such as TCF21, SLC5A8, ID4, BMP3B, and SOCS1 have been identified by RLGS." (PMID 18053125, 2007). "We could not detect a correlation between SLC5A8 expression and tumor focality or invasion, which was reported previously, nor with tumor size." (PMID 40869209, 2025). "In contrast, in the patient showing re-induction of RAI uptake following treatment with larotrectinib, her tumor was negative for TERT promoter mutations and showed high TDS with no downregulation of the apical iodide transporter (SLC5A8) and the sodium–iodide symporter (SLC5A5) gene expression." (PMID 38642578, 2024). "Furthermore, Xing M demonstrated that activation of MAPK signaling pathway resulted in upregulation of tumor-promoting genes (e.g. VEGFA, MET, HIF1A, UPA, UPAR, TGFB1, and TSP1) as well as downregulation of tumor suppression and thyroid genes (e.g. TIMP3, SLC5A8, DAPK1, NIS, TSHR, and TPO)." (PMID 35600399, 2022). "In this paper, Migdalska-Sek at al. assessed and compared the methylation level of 8 tumor suppressor genes, ARHI, CDH1, KCNQ1, MEST, p16INK4A, RASSF1A, SLC5A8 and VHL in PTC tumor tissues and matched adjacent noncancerous thyroid tissues." (PMID 25490036, 2014). "The maximum separation between tissue types (normals, as opposed to tumour tissue plus cell lines) occurred with the transcript combination of MMP-7, RECK and SLC5A8." (PMID 19689820, 2009).